DPP4 (dipeptidyl peptidase 4)
Diseases named in the same sentence as DPP4 in open-access papers (continued):
Sharing a sentence is not in itself a finding about the gene and the disease.
type 2 diabetes (continued). "Of these substrates, SDF-1α is the most potent chemokine known to induce cardiovascular protection by DPP-4 inhibitors, because it has been reported that the levels of serum SDF-1α and endothelial progenitor cells increased with oral DPP-4 inhibitor treatment in patients with type 2 diabetes." (PMID 25407968, 2014). "However, randomized clinical trials failed to prove potential CV protective actions of DPP-4 inhibitor in patients with type 2 diabetes." (PMID 25140306, 2014). "Moreover, combination studies with AGIs on top of treatment with a DPP-4 inhibitor in type 2 diabetic patients, showed further increase of the area under the curve (AUC) of plasma GLP-1 concentrations after a meal, compared to therapy with the DPP-4 inhibitor alone." (PMID 24742256, 2014). "This cohort study evaluates whether older adults with type 2 diabetes and cancer have improved survival when taking glucagon-like peptide-1 receptor agonists (GLP-1RAs) compared with sodium-glucose cotransporter-2 inhibitors and dipeptidyl peptidase-4 inhibitors." (PMID 40679827, 2025). "In our study, we could not demonstrate that DPP4 inhibitors have significant action on platelet reactivity in patients with type 2 diabetes hospitalized for acute myocardial infarction using DAPT at 4 days after randomization (primary endpoint) or at 30 days (secondary endpoint)." (PMID 36233642, 2022). "Dipeptidyl peptidase-4 inhibitors (DPP-4i), as one of common antidiabetic reagents, are currently recommended for the first-line hypoglycemic treatment of type 2 diabetes mellitus (T2DM)." (PMID 34631556, 2021). "The use of DPP4 inhibitors, such as gliptins, in COVID-19 patients with or without type 2 diabetes may provide a convenient strategy to minimize viral entrance and reproduction into the airways, as well as to lessen the long-term cytokine storm and inflammation in the lungs has been studied." (PMID 35822018, 2021). "Whether glucagon counter-regulation to hypoglycemia is affected during DPP-4 inhibition in type 2 diabetes has been studied in drug-naïve subjects, in subjects when a DPP-4 inhibition was added on to insulin therapy, and in elderly subjects with metformin-treated type 2 diabetes." (PMID 31275243, 2019). "In this study, to examine which factors could influence the durability of DPP-4 inhibitor in subjects with type 2 diabetes, we analyzed retrospectively 212 outpatients who were treated with DPP-4 inhibitor for over 12 months without an addition or increase of other antidiabetes agents." (PMID 28626771, 2017). "However, it has not been fully elucidated whether DPP-4 inhibitors are able to improve endothelial function in patients with type 2 diabetes." (PMID 27711199, 2016). "A recent study revealed that alogliptin, a DPP-4 inhibitor, did not increase the frequency of serious adverse events, including hypoglycemia, cancer, pancreatitis, and initiation of dialysis in patients with type 2 diabetes who had a recent acute coronary syndrome." (PMID 25074318, 2014). "Despite the absence of monoclonal antibodies against known type-2 diabetes small molecule targets ABCC8, ABCC9, DPP4, and KCNJ11, these genes demonstrated AB tractability estimates greater than 60%, along with interleukin receptors IL4R and IL17RA." (PMID 37225853, 2023). "Consistent with our results, DPP4 inhibitors and GLP‐1 analogs have not been found to significantly improve insulin sensitivity in patients with type 2 diabetes." (PMID 36585794, 2023). "Linagliptin, a DPP-4 inhibitor, reduces CCL2, CCL22, and IL-12 in type 2 diabetes patients with or without DN compared with the placebo group, suggesting its anti-inflammatory abilities in type 2 DM." (PMID 32365893, 2020). "DPP-4 inhibitor increases GLP-1 and CXCL12 in type 2 diabetes patients with or without DN compared with the placebo group, suggesting its pro-vasculoregenerative ability in type 2 DM." (PMID 32365893, 2020).
type 2 diabetes (continued). "Our study population included patients with type 2 diabetes (ICD-9-CM 250) between 2009 and 2012, and the study groups were DPP-4 inhibitor users and nonusers." (PMID 31013793, 2019). "GLP-1 receptor agonists that are not substrates of DPP-4 and DPP-4 inhibitors are approved for the treatment of type 2 diabetes." (PMID 29997575, 2018). "Recent renal outcome trails with agents such as thiazolidinediones, DPP-4 inhibitors, bardoxolone, and sulodexide have been unsuccessful; however, exciting new data from trials with GLP1R agonists and SGLT2 inhibitors show beneficial renal effects in patients with type 2 diabetes mellitus (T2DM)." (PMID 29629372, 2018). "Despite encouraging preclinical data and the success of DPP-4 inhibitors, progression of enzyme-resistant GIP-based drugs to the type 2 diabetes clinic is lacking." (PMID 28004148, 2017). "Though our follow up studies affirmed high DPP4 expression at the protein level, clinical evaluation of the HESN cohort did not confirm type 2 diabetes but an impaired fasting glucose state." (PMID 22291902, 2012). "We previously reported in the study of preventive effects of alogliptin on diabetic atherosclerosis (SPEAD-A) that alogliptin, a dipeptidyl peptidase-4 (DPP-4) inhibitor, attenuated the progression of carotid atherosclerosis in subjects with type 2 diabetes and no history of cardiovascular disease." (PMID 37669959, 2023). "However, two recent trials with DPP-4 inhibitors, SAVOR-TIMI 53 and EXAMINE trials, showed that saxagliptin and alogliptin did not increase or decrease ischemic events in patients with type 2 diabetes." (PMID 25074318, 2014). "This case highlights the potential of combining a DPP-4 inhibitor (sitagliptin) with an SGLT2 inhibitor (empagliflozin), which may help improve glycemic control in a patient with CMT complicated by type 2 diabetes and appears not to have compromised skeletal muscle mass." (PMID 40951209, 2025). "Combination therapy adding the dipeptidyl peptidase-4 (DPP-4) inhibitor, saxigliptin to concurrent metformin therapy for 12 weeks was found to increase CD31+ numbers (reflecting a mature circulating pool of endothelial cells) but not CD34+ in type II diabetes patients." (PMID 35909294, 2023). "Although dipeptidyl peptidase-4 (DPP-4) inhibitors have been suggested to have a non-glucoregulatory protective effect in various tissues, the effects of long-term inhibition of DPP-4 on the micro- and macro-vascular complications of type 2 diabetes remain uncertain." (PMID 26959365, 2016). "The fasting serum DPP-4 enzymatic activity (sDPP-4) was measured in patients with NAFLD and in similarly obese patients with type 2 diabetes but without clinically evident liver disease (defined as T2D group) and also in healthy controls (CNTRL)." (PMID 20805868, 2010).
Hypoglycemia (262 papers, 2008 to 2026). A decreased concentration of glucose in the blood. "Within this framework, guidelines indicate that therapies involving DPP‐4 inhibitors or SGLT‐2 inhibitors are linked with minimal hypoglycemia risk." (PMID 40309616, 2025). "A majority (86.3%) understood that DPP-4 inhibitors are associated with a minimal risk of hypoglycemia." (PMID 40734861, 2025). "By contrast, therapeutic agents with a low hypoglycemia risk, such as DPP-4 inhibitors and SGLT2 inhibitors, are linked to lower cardiovascular event rates." (PMID 41384191, 2025). "For example, sitagliptin, a DPP-4 inhibitor, is generally well tolerated and has a low risk of hypoglycemia, making it a suitable option for elderly patients or those with renal impairment." (PMID 41573193, 2025). "DPP-4 inhibitors are generally well tolerated in older patients due to their low hypoglycemia risk and weight neutrality, which reduces the likelihood of adverse events." (PMID 39768866, 2024). "As a drug with a high risk of hypoglycaemia, 144 patients were taking SU, and two were taking glinide; the other two patients were taking dipeptidyl peptidase 4 inhibitors (DPP4i) alone." (PMID 38975379, 2024). "The low risk of hypoglycemia associated with DPP-4 inhibitors makes them an attractive option for this population." (PMID 39768866, 2024). "Unlike sulfonylureas or insulin, which are associated with higher rates of hypoglycemia, DPP-4 inhibitors such as alogliptin generally exhibit a low risk of hypoglycemia, and this was observed in the EXAMINE trial as well." (PMID 39768866, 2024). "Despite these risks, DPP-4 inhibitors have advantages like lower hypoglycemia risk and weight management benefits." (PMID 39121166, 2024). "DPP-4 inhibitors, with their glucose-dependent insulin secretion, low risk of hypoglycemia, and weight neutrality, provide an attractive option for these patients." (PMID 39768866, 2024). "In comparison to other antidiabetic therapies, DPP-4 inhibitors are preferable to agents associated with hypoglycemia and weight gain, though SGLT2 inhibitors exhibit superior benefits in heart failure." (PMID 39768866, 2024). "SGLT2 inhibitors and DPP-4 inhibitors demonstrated a low risk of hypoglycemia when used as monotherapy or in combination with metformin." (PMID 39723311, 2024). "DPP-4 inhibitors are generally well tolerated and have a low risk of hypoglycemia compared to other antidiabetic drugs." (PMID 38792165, 2024). "DPP-4 inhibitors have been demonstrated to effectively lower FG, postprandial glucose, and HbA1c levels while maintaining a low risk of hypoglycemia." (PMID 39203828, 2024). "This aligns with findings that DPP-4 inhibitors reduce hypoglycemia risk when combined with sulfonylureas and are as effective as GLP-1 analogs." (PMID 39121166, 2024). "DPP-4 inhibitors have been used in T2D and have good tolerability and can even reduce the risk of hypoglycemia." (PMID 39594662, 2024). "Addition of dipeptidyl peptidase-4 inhibitors to sulphonylureas and risk of hypoglycaemia: systematic review and meta-analysis." (PMID 39119157, 2024). "DPP-4 inhibitors are effective in controlling blood glucose levels, have a low risk of hypoglycemia, are well tolerated in patients with T2D and diabetic kidney disease (DKD), and are expected to reduce the progression of diabetic nephropathy." (PMID 39135967, 2024). "DPP-4 inhibitors are considered good options for older patients because of their efficacy and low risk of hypoglycaemia." (PMID 37287751, 2023). "Dipeptidyl peptidase-4 inhibitors increase glucagon-like peptide-1 and thus, decrease blood glucose levels with low risk of hypoglycemia." (PMID 38057844, 2023). "To conclude, newer medications are associated with a lower risk of hypoglycemia compared to sulfonylureas, and DPP-4 inhibitors are particularly effective in reducing this risk." (PMID 38169925, 2023).
Hypoglycemia (continued). "In fact, DPP-4 inhibitors are now replacing the use of sulphonylureas as insulin-releasing agents due to their insulin-tropic effect, and notably because DPP-4 inhibitors reduce the intrinsic risk of low blood sugar or hypoglycaemia." (PMID 37287751, 2023). "The meta-analysis indicates that DPP-4 inhibitors would significantly reduce the risk of hypoglycemia as compared to sulphonylurea (odds ratio = 0.38, 95% CI: 0.26 to 0.55, p < 0.00001)." (PMID 35242880, 2022). "Sulfonylureas and glinides are usually avoided due to the risk of hypoglycemia, as are incretin-based therapies (DPP4 inhibitors and GLP-1 analogs) due to underlying pancreatic disease." (PMID 36422243, 2022). "Among these strategies, the use of dipeptidyl peptidase-4 (DPP-4) inhibitors is receiving wider attention due to its advantage of low risk of hypoglycemia." (PMID 36429217, 2022). "The risk of hospitalisations for hypoglycaemia was 31% lower in patients initiating SGLT2 inhibitors compared to DPP4 inhibitors in our study." (PMID 35673518, 2022). "DPP-4 inhibitors carry a very low risk of hypoglycemia and also exert anti-atherosclerotic effects through many mechanisms, which makes them more suitable for these patients." (PMID 36611464, 2022). "We suggest that DPP-4 inhibitors are an appropriate and suitable choice for diabetic dialysis patients who are at high risk of hypoglycemia, regarding monotherapy or add-on treatment." (PMID 34496858, 2021). "As a new class of anti-diabetic drugs, dipeptidyl peptidase-4 (DPP-4) inhibitors exhibit many favorable features, such as a low risk of hypoglycemia, weight neutrality, and a lower glycemic variability with comparable glucose control capability." (PMID 34616361, 2021). "Dipeptidyl peptidase-4 (DPP4) inhibitors are associated with low risk of hypoglycaemia and are relatively safe across a wide range of renal functions." (PMID 32405783, 2020). "Those treated with either gliclazide or dipeptidyl peptidase-4 inhibitors had a comparable low risk of symptomatic hypoglycemia." (PMID 32151247, 2020). "Although severe hypoglycemia has been reported even with the single usage of SU, a meta-analysis of combination therapy efficacy of DPP-4 inhibitors with SU in patients with T2DM showed that the risk of hypoglycemia was increased by approximately 50%." (PMID 32518665, 2020). "For DPP-4 inhibitors the position statement focused on their low risk of hypoglycemia and also that it can be given in a large group of subjects, including those with reduced renal function." (PMID 31275243, 2019). "This low risk of hypoglycemia with DPP-4 inhibition is also underlined in guidelines and position documents." (PMID 31275243, 2019). "This increased risk for hypoglycemia with this combination has later been confirmed in other studies and a meta-analysis showed an approximately 50% increased risk for hypoglycemia when DPP-4 inhibitors are combined with sulfonylurea." (PMID 31275243, 2019). "Incretin-based therapies (GLP-1 analogs and DPP-4-inhibitors) are thus frequently used for the treatment of T2DM with a minimum risk for hypoglycemia." (PMID 31126115, 2019). "An overall experience in studies with DPP-4 inhibitors was that they have a low risk of adverse events, including hypoglycemia." (PMID 31275243, 2019). "One of the common T2DM medications, dipeptidyl peptidase (DPP)-4 inhibitors, have a minimum risk for hypoglycemia and have recently been suggested to ameliorate β-amyloid pathology." (PMID 31126115, 2019). "The DPP-4 inhibitors have neutral effects on body weight or risk of hypoglycemia (justified by the glucose-dependent insulin secretion mode of action of GLP-1), except when there is concomitant treatment with insulin or sulfonylureas." (PMID 31366085, 2019). "The DPP-4 inhibitor is already a favorable antidiabetic medication due to its neutral effect on body weight and relatively low risk of hypoglycemia." (PMID 31627406, 2019).
Hypoglycemia (continued). "The insulinotropic effect of DPP-4 inhibitors explains the phenomenon that this class increasingly is replacing the use of sulfonylureas as insulin releasing agents; especially since the intrinsic hypoglycaemia risk of DPP-4 inhibitors is very low." (PMID 31275246, 2019). "In the adjusted Cox model, the use of NPH compared to that of DPP-4 inhibitors was associated with a higher risk of discontinuation (HR: 1.33; 95% CI 1.27–1.40) and hypoglycemia (HR: 2.98; 95% CI 2.72–3.28)." (PMID 29713649, 2018). "Salvo F, Moore N, Arnaud M, Robinson P, Raschi E, De Ponti F, Bégaud B, Pariente A. Addition of dipeptidyl peptidase-4 inhibitors to sulphonylureas and risk of hypoglycaemia: systematic review and meta-analysis." (PMID 29527102, 2018). "It is unlikely that DPP4 inhibitors cause hypoglycemia when used alone or in combination with metformin, due to the glucose-dependent effects on insulin and glucagon secretion." (PMID 29535389, 2018). "Dipeptidyl peptidase-4 (DPP-4) inhibitors are now established as oral glucose-lowering drugs with little intrinsic risk of causing hypoglycemia or weight gain." (PMID 29540217, 2018). "Overall, results were comparable with those found in the RCTs, suggesting that the use of incretin mimetics, specifically DPP-4 inhibitors were associated with a lower risk of hypoglycemia." (PMID 26765440, 2016). "Monotherapy with biguanides or dipeptidyl peptidase-4 inhibitors is associated with a lower risk of inducing hypoglycemia than sulfonylurea treatment." (PMID 27843494, 2016). "Dipeptidyl peptidase-4 (DPP-4) inhibitors have several potential advantages intreating people with CKD as they are associated with a low risk of hypoglycemia and areweight-neutral." (PMID 27460913, 2016). "Accordingly, sulfonylureas are associated with risk of hypoglycemia and weight gain; DPP-4 inhibitors are associated with lower frequency of hypoglycemia and are weight neutral." (PMID 26925169, 2016). "Because the effects of GLP-1 on insulin secretion are glucose-dependent, the risk of hypoglycemia associated with DPP4 inhibitor treatment is low." (PMID 26021829, 2015). "In the active drug comparisons, insulin glargine and all SUs were associated with significantly higher rates of confirmed hypoglycemia compared to any SGLT2 or DPP-4 inhibitor (RR range, 4.32–71.29)." (PMID 25919293, 2015). "Previous reports have suggested that patients treated with DPP4 inhibitors have a low risk for hypoglycemia even under irregular eating patterns." (PMID 25946187, 2015). "Similar trends were found in analysis with combined therapies, a strong association with not only insulin but also SU agents and glinides, a low risk of hypoglycemia when using DPP-4 inhibitors." (PMID 26566411, 2015). "DPP-4 inhibitors, which have been shown in meta-analysis to be associated with a low incidence of hypoglycemia and little risk of weight gain, are useful to achieve therapeutic targets." (PMID 26550558, 2015). "In line with our own results, most trials comparing a DPP-4 inhibitor with SU, in combination with metformin, demonstrate a slightly higher risk of hypoglycaemia in the latter group." (PMID 25645672, 2015). "For example, the use of sulfonylureas has declined in favor of drugs that are less likely to cause hypoglycemia, such as metformin and DPP-4 inhibitors." (PMID 26252486, 2015). "The use of sulphonilureas should be restricted in the elderly, favoring the use of antidiabetic drugs with a low risk of hypoglycemia (metformin, DPP-4 inhibitors)." (PMID 25519433, 2014). "DPP-4 inhibitors are associated with a lower incidence of hypoglycemia than conventional hypoglycemic drugs." (PMID 23432786, 2013). "•DPP-4 inhibitors have a low risk of hypoglycemia due to their effect as glucose-dependent insulin secretagogue." (PMID 23697612, 2013).